RNU6-91P (RNA, U6 small nuclear 91, pseudogene)
Gene: Small nuclear RNA gene on chromosome 14 (99,444,306 to 99,444,412, forward strand). Ensembl gene ENSG00000272439.
Homologues: Orthologues: chimpanzee U6 (99% identical), macaque U6 (95% identical), dog U6 (85% identical), mouse Gm23379 (85% identical), rat U6 (85% identical), rabbit U6 (75% identical), pig U6 (73% identical). Paralogues in human: RNU6-1 (87% identical), RNU6-2 (87% identical), RNU6-3P (87% identical), RNU6-4P (87% identical), RNU6-5P (87% identical), RNU6-6P (87% identical), RNU6-9 (87% identical), RNU6-1024P (86% identical), RNU6-116P (86% identical), RNU6-12P (86% identical), RNU6-13P (86% identical), RNU6-140P (86% identical), and 1289 more.